ABCG1 (ATP binding cassette subfamily G member 1)
Diseases named in the same sentence as ABCG1 in open-access papers (continued):
Sharing a sentence is not in itself a finding about the gene and the disease.
atherosclerosis (continued). "Although ABCG1 was initially proposed to mediate cholesterol efflux from macrophages and then to protect against atherosclerosis and cardiovascular diseases (CVD), it becomes now clear that ABCG1 exerts a larger spectrum of actions which are of major importance in cardiometabolic diseases (CMD)." (PMID 28869506, 2017). "Significantly, transplantation of bone marrow cells with genetic knockout of Abca1 and Abcg1 into mouse models prone to developing atherosclerosis resulted in accelerated atherosclerosis, underscoring an athero-protective role for these transporters in myeloid cells." (PMID 29069761, 2017). "Double-knockout (ABCA1−/−/ABCG1−/−)mice displayed accelerated atherosclerosis development and observed massive foam cell formation in the myocardium, lung, liver, Peyer’s patches, lymph nodes, and spleen, and increased secretion of inflammatory cytokines and chemokines." (PMID 29113088, 2017). "Thus, ABCA1- and ABCG1-driven cholesterol efflux in macrophages was a key regulator in anti-atherosclerosis." (PMID 27328813, 2016). "Therefore, the Sirt1-LXR-ABCA1/ABCG1 signaling pathway is involved in the regulation of cholesterol efflux and is inhibited during the initiation and progression of atherosclerosis, resulting in cholesterol uptake by macrophages and foam cell formation." (PMID 27744418, 2016). "Therefore, it was presumed that ABCG1 knockout in macrophages would result in increased foam cells and atherosclerosis." (PMID 24972087, 2014). "Indeed, the key genes enriched in the cholesterol binding pathway have links to cholesterol efflux (ABCG1), inflammation, and atherosclerosis (ABCB1 and APOA2)." (PMID 24763700, 2014). "The role of ABCG1 in atherosclerosis remains controversial, especially in animal models." (PMID 24972087, 2014). "Therefore, this study furthers the understanding of the role of ABCG1 in atherosclerosis and its potential value as a disease marker." (PMID 24972087, 2014). "Changes in cellular SM levels may be involved in regulating the function of ABCA1 and ABCG1, and in the development of atherosclerosis." (PMID 25302608, 2014). "ABCG1 might be expected to be inhibitory of atherosclerosis development by promoting macrophage efflux." (PMID 24314261, 2013). "One particularly promising area of research may be to investigate the role of ABCG1 on endothelial function in DS, given that studies in preclinical models suggest that excess ABCG1 may promote endothelial resistance to triggers of atherosclerosis." (PMID 22649448, 2012). "Although these mechanisms have yet to be examined in DS subjects, abundant ABCG1 function in the endothelium may help to explain their relative protection from atherosclerosis." (PMID 22649448, 2012). "Nonetheless, in ABCG-1 knockout mice the development of atherosclerosis is still controversial." (PMID 21957962, 2011). "Thus, it has been proposed that increasing ABCG1 expression may have protective effects against atherosclerosis development." (PMID 40356723, 2025). "Hence, scrutinising the mechanisms governing ABCG1 expression could hold significance for devising a novel therapeutic strategy for atherosclerosis." (PMID 39804798, 2025). "Using this technology, we show that global loss of Abcg1 does not alter atherosclerosis regression." (PMID 39088185, 2024). "In our study we show no impact of loss of Abcg1 on atherosclerosis regression." (PMID 39088185, 2024). "However, loss of Abcg1 did not impact atherosclerosis regression in either the aortic root or in aortic arch, demonstrating no important role for this transporter subtype." (PMID 39088185, 2024).
atherosclerosis (continued). "Notably, Qing-Xue-Xiao-Zhi formula (QXXZ, 清血消脂方), Si-Ni decoction (四逆汤), Qi-Shen-Yi-Qi Pill (芪参益气丸), and Yin-Xing-Tong-Mai decoction (银杏通脉汤) have been demonstrated to attenuate hyperlipidemia and atherosclerosis by facilitating RCT through upregulation of PPARγ–LXRα–ABCA1/ABCG1 signaling pathways." (PMID 38699583, 2024). "Thus, the data available to date suggest that ABCG1 may play a positive role in the prevention of atherosclerosis, but its clinical significance is still unclear and requires new studies." (PMID 39857239, 2024). "Since liver X receptor (LXR), a nuclear receptor, regulates the expression of genes involved in cholesterol efflux, including Abca1, Abcg1, and Apoe, in atherosclerosis and aged mice, we examined whether the LXR agonist, GW3965, promotes cholesterol efflux from spinal cord lesions." (PMID 37223476, 2023). "However, it is largely unknown whether and how asprosin has an effect on ABCA1 and ABCG1 expression and atherosclerosis." (PMID 35902881, 2022). "Therefore, it is possible that genetic manipulation of ABCA1/ABCG1 in certain cells or tissues at different stages of life may influence atherogenesis or atherosclerosis progression differently." (PMID 35625607, 2022). "However, ABCG1 could protect from atherosclerosis by preserving vascular endothelium from dietary cholesterol-induced dysfunction." (PMID 28869506, 2017). "Thus, Sirt1 may prevent the generation and progression of atherosclerosis by enhancing the LXR-ABCA1/ABCG1/CCR7 pathway to suppress foam cell formation." (PMID 27744418, 2016). "Thus, the activation of cholesterol efflux pathways targeting ABCA1 and ABCG1 may prove to be novel therapeutic approaches to the treatment of atherosclerosis." (PMID 25673178, 2015). "Therefore, the role of ABCG1 in atherosclerosis remains controversial, especially in animal models." (PMID 24972087, 2014). "This questions whether ABCG1 plays an equally critical role in preventing atherosclerosis." (PMID 21829447, 2011). "However, a human disease caused by ABCG1 dysfunction has not been identified and ABCG1 deficiency in animal studies has not consistently shown evidence of increased atherosclerosis." (PMID 21829447, 2011). "In the progression of atherosclerosis, ABCA1 and ABCG1 play critical roles in mediating cholesterol efflux from macrophages to HDL." (PMID 38600398, 2025). "The next critical step in understanding the pathophysiology of atherosclerosis involves characterizing the precise structural and functional consequences of oxidative stress on ABCA1 and ABCG1." (PMID 41300518, 2025). "A different study has also indicated that ABCG1, degraded by UPS, potentially functions as a bridge in USP18‐regulated lipid metabolism during the development of atherosclerosis." (PMID 39804798, 2025). "The genes for ABC transporters ABCA1 and ABCG1 are LXR targets and ABCA1 and ABCG1 strongly influence atherosclerosis both LXR-dependently and LXR-independently." (PMID 40305368, 2025). "In atherosclerosis, the expression of ABCA1 and ABCG1 is decreased, which aggravates the accumulation of cholesterol and formation of foam cells." (PMID 38600398, 2025). "Studies have shown that AMPK prevented the development of atherosclerosis-related cardiovascular disease by upregulating the expression of ABCA1 and ABCG1 in macrophages and promoting HDL-regulated cholesterol efflux in macrophages." (PMID 38999750, 2024). "Deficiency of HDAC9 promotes cholesterol efflux from macrophages and reduces plaque area in atherosclerosis‐prone mice by enhancing the expression of ABCA1 and ABCG1." (PMID 39698913, 2024).
atherosclerosis (continued). "A similar expression pattern is visible in other inflammation and atherosclerosis related genes such as APOE, KLF4, CXC3L1, STC1, CH25H, and ABCG1." (PMID 39695567, 2024). "However, unlike ABCA1, the deficiency of which is associated with Tangier disease characterized by low HDL levels and early development of atherosclerosis, there are no data on a similar pattern for ABCG1 deficiency, which is probably compensated for by the ABCA1 function." (PMID 39857239, 2024). "For example, betulin can reduce atherosclerosis by upregulating ABCA1 and ABCG1 expression 39 or inhibiting the degradation of ABCA140." (PMID 36923537, 2023). "Heat shock protein 70 (HSP70) accelerates atherosclerosis by downregulating the expression of ABCA1 and ABCG1 through the JNK signaling pathway." (PMID 37021059, 2023). "In conclusion, moxonidine inhibited atherosclerosis in ApoE−/− mice, which was accompanied by an increase in oxidised LDL uptake by VSMCs, VSMC migration, ABCG1 expression in VSMCs and lipid hydroperoxide levels in the plasma." (PMID 36835270, 2023). "LXRα, an important regulator of cholesterol efflux in atherosclerosis, has been shown to be down‐regulated in oxLDL‐treated macrophages, as its downstream membrane proteins ABCA1 and ABCG1 were concomitantly decreased." (PMID 37905351, 2023). "The main mechanisms of chlorogenic acid in inhibiting atherosclerosis include increased synthesis and mRNA expression of PPARγ, LXRα, ABCA1 and ABCG1, as well as transcriptional activity resulting from PPARγ activation." (PMID 37432383, 2023). "Collectively, these results suggest that AG ameliorates atherosclerosis via inhibiting inflammation and improving cholesterol efflux by inhibiting the TLR4/NF-κB pathway by up-regulating ABCA1 and ABCG1." (PMID 37920216, 2023). "Since these subsets have both pro- and anti-inflammatory effects, and the loss of Abca1/Abcg1 in T cells does not affect a single predominant T cell subset, this effect on atherosclerosis could be due to counter-regulatory inflammatory effects in the aorta during sterile inflammation." (PMID 35778407, 2022). "Acetylation of PPARγ at K268/K293 increases atherosclerosis through upregulating ABCA1, ABCG1, and NcoR but inhibiting PRDM16, while deacetylation of PPARγ at K268 and K293 alleviates atherosclerosis." (PMID 35309069, 2022). "We demonstrated that compared to patients with stenotic atherosclerosis, patients with AAA had altered HDL metabolism and functions involved in their anti-inflammatory and tissue repair activity, particularly through the ABCG1-related intracellular signaling." (PMID 36172376, 2022). "ABCA1, ABCG1, and scavenger receptor class B type 1 (SRB1) promote cholesterol efflux and exchange of cholesterol to influence atherosclerosis in mice." (PMID 34095317, 2021). "For ABCA1, lncRNA CDKN2B-AS1 also significantly decreases the ABCG1 level in human foam cells, inhibiting the expression of CDKN2B, which can lead to the suppression of RCT and progression of atherosclerosis." (PMID 34940525, 2021). "Together, these studies indicate that decreased expression of ABCG1 in macrophages contributes to the downregulation of cholesterol efflux to HDL particles and RCT impairment that leads to the development of atherosclerosis." (PMID 34940525, 2021).
atherosclerosis (continued). "LncRNA TUG1, which is associated with the development of atherosclerosis, reduces the expression of not only ABCA1 but also ABCG1 at the RNA and protein levels, which probably decreases RCT effectiveness and atherosclerosis progression." (PMID 34940525, 2021). "Therefore, DNA methylation of ABCA1 and ABCG1 could be involved in atherosclerosis development." (PMID 34837967, 2021). "While our findings in vitro suggest that rHDL + T1317 combination therapy can upregulate ABCA1 and ABCG1 at the mRNA and protein level as well as increase TC efflux when compared to either drug alone, we wanted to confirm whether these findings confer a greater anti-atherosclerosis effect in vivo." (PMID 33390931, 2020). "In conclusion, we found DNA methylation in ABCG1 and APOE to be related to ischemic stroke and atherosclerosis in a Chinese population." (PMID 31823830, 2019). "Hemodynamic changes that occur during the development of atherosclerosis, including low sheer stress and turbulent flow, alter the expression of both LXR isoforms and their target genes Abca1 and Abcg1." (PMID 30087224, 2018). "The expression of positive regulators of atherosclerosis (ABCA1, ABCG1) was higher in the P group than that in the RP group (P < 0.05), and the opposite effect was observed for negative regulators (ACAT1, CD36)." (PMID 30105261, 2018). "For this reason, current therapeutic perspectives in atherosclerosis aim at promoting cholesterol efflux by a process resulting in an increase in ABCA1 and ABCG1 expression that generates higher amount of HDL." (PMID 27252658, 2016). "For example, activation of the Liver X receptor (LXR) signaling pathway regulating the ABCA1/ABCG1 expression have been shown to promote macrophage RCT and decrease atherosclerosis in mouse models." (PMID 27252658, 2016). "The induction of ATP-binding cassette transporter family members, such as ABCA1 and ABCG1, by LXR activation can enhance reverse cholesterol transport and reduce atherosclerosis." (PMID 27250582, 2016). "Studies show that the activation of LXRα, one of the LXRs, attenuates the atherosclerosis formation by an increase in expression of cholesterol efflux transporters ABCA1 and ABCG1 in macrophages, and excretion transporters ABCG5 and ABCG8 in enterocytes." (PMID 27399689, 2016). "ATP-binding cassette transporter G1 (ABCG1) is a transmembrane cholesterol transporter involved in macrophage sterol homeostasis, reverse cholesterol transport (RCT), and atherosclerosis." (PMID 24972087, 2014). "Among the ABC transporters, ABCG1 and ABCA1 are well-known for their roles in cholesterol efflux, which is essential for maintaining lipid homeostasis and preventing the formation of lipid-laden macrophages in atherosclerosis." (PMID 41252867, 2025). "Our results showed that by upregulating the PPARγ-ABCA1/ABCG1/SR-B1 pathway, ART could enhance cholesterol efflux and ameliorate inflammation, thereby alleviating atherosclerosis." (PMID 40867523, 2025). "The deletion of ABCA1 and ABCG1 in macrophages accelerates the development of atherosclerosis in LDL receptor-knockout mice, underscoring the pivotal role of cholesterol efflux mediated by ABCA1 and ABCG1 in preventing atherosclerosis." (PMID 40537740, 2025). "ATP-binding cholesterol transporters ABCG1 and ABCA1 export cholesterol from macrophages in the vessel wall to HDL and ApoA-1, reducing lipid deposition and preventing foam cell formation, thereby attenuating atherosclerosis (Ouimet, Barrett & Fisher, 2019)." (PMID 39421410, 2024). "Lacking of ABCG1 in mice increases early atherosclerosis lesions but delays the progression of advanced atherosclerotic lesions." (PMID 38896016, 2024). "Indeed, the overexpression of either ABCA1 or ABCG1 heightens HDL levels and confers protection against atherosclerosis." (PMID 38474781, 2024).
atherosclerosis (continued). "Cholesterol levels may be also reduced by Hsp25 immunotherapy, Hsp25 reduces plaque cholesterol by 30% and prevents experimental atherosclerosis in mice, which requires GM-CSF-regulated ABCA1 and ABCG1 expression." (PMID 37077734, 2023). "Baicalin may prevent atherosclerosis by increasing cholesterol efflux from macrophages and delaying the production of foam cells via the PPAR-LXR-ABCA1/ABCG1 pathway." (PMID 35607519, 2022). "Thus, asprosin suppresses macrophage lipid accumulation and mitigates atherosclerosis by promoting ABCA1- and ABCG1-dependent cholesterol efflux." (PMID 35902881, 2022). "Thus, ABCA1 and ABCG1, which are a link in reverse cholesterol transport, along with HDL demonstrate involvement in the pathogenesis of COPD and its comorbid links with atherosclerosis." (PMID 35897703, 2022). "In addition, the ABCA1 and ABCG1 transporters are an important link between COPD and atherosclerosis." (PMID 35897703, 2022). "Regarding the ABCA1 and ABCG1 induction mechanisms, liver X receptor (LXR) agonists are the most well-identified transcription factors to stimulate ABCG1 and ABCA1 expression, resulting in promotion of cholesterol efflux from macrophages, and eventually protection against atherosclerosis in mice." (PMID 34445501, 2021). "Together, methylation of the ABCG1 promoter region downregulates its transcription, and HDL-C deficit may contribute to atherosclerosis." (PMID 34940525, 2021). "As ABCG1 is involved in RCT, a change in its expression in atherosclerosis can be expected." (PMID 34940525, 2021). "Thus, promotion of ABCA1- and ABCG1-mediated cholesterol efflux is a key mechanism by which CTRP12 suppresses macrophage lipid accumulation and mitigates atherosclerosis." (PMID 33692340, 2021). "ABCA1, ABCG1, and HDL are potential targets for the treatment of atherosclerosis." (PMID 34350368, 2020). "ABCA1, ABCG1, ACAT1, and CD36 are positive or negative regulators of atherosclerosis." (PMID 30105261, 2018). "Therefore, the existence of an AP-1/miR-378/ABCG1 regulatory axis can be proposed that links CoQ10 to macrophage cholesterol efflux to HDL and atherosclerosis." (PMID 31304263, 2018). "ABCG1 has also mostly been studied in the context of atherosclerosis, however there are currently no reported genetic ABCG1 mutations reported that are associated with an increased risk for cardiovascular disease in humans." (PMID 28241820, 2017). "Mice deficient in the p50 subunit of NFκB on a high-cholesterol diet are protected from IH-induced ABCA1 inhibition and accelerated atherosclerosis, suggesting that ABCA1 and ABCG1 inhibition in IH may be mediated by NFκB activation." (PMID 26738794, 2016). "As TGF-β downregulates scavenger receptors, such as scavenger receptor type A (SR-A) I/II and CD36, and upregulates ATP-binding cassette (ABC) transporters, ABCA1 and ABCG1, TGF-β is also thought to have protective effects against the development of atherosclerosis." (PMID 21199582, 2011). "During the development of atherosclerosis, macrophages regulate intracellular cholesterol homeostasis by scavenger receptor SRA-mediated cholesterol uptake and ATP-binding cassette transporter G1 (ABCG1)-mediated cholesterol efflux, thereby maintaining intracellular cholesterol homeostasis 61-63." (PMID 40225574, 2025). "However, no study to date has specifically investigated the role of ABCG1 in atherosclerosis regression." (PMID 39088185, 2024). "Thus, the role of ABCG1 in macrophages in atherosclerosis, in contrast to ABCA1, is still not sufficiently clear and requires new studies." (PMID 39857239, 2024). "Atherosclerosis is a process that develops in the vascular wall over many years as a result of a complex chain of events involving immune and metabolic mechanisms in which ABC transporters, including ABCG1, may be involved." (PMID 39857239, 2024).